B4GALNT2 (beta-1,4-N-acetyl-galactosaminyltransferase 2 (SID blood group))
Diseases named in the same sentence as B4GALNT2 in open-access papers (continued):
Sharing a sentence is not in itself a finding about the gene and the disease.
congenital muscular dystrophy (1 paper, 2024). A muscular dystrophy that is characterized by diminished muscle tone (hypotonia), progressive muscle weakness and degeneration (atrophy), abnormally fixed joints, spinal rigidity, and delays in reaching motor milestones such as sitting or standing unassisted. "The manipulation of B4GALNT2 expression can affect the expression of several modifiers associated with muscular dystrophy, and the deletion of this gene exacerbates the severity of congenital muscular dystrophy in mice." (PMID 38540389, 2024). "Additionally, the B4GALNT2 gene has been implicated in congenital muscular dystrophy, and its expression in the muscles of mice is dynamic." (PMID 38540389, 2024).
COVID-19 (1 paper, 2024). A disease caused by infection with severe acute respiratory syndrome coronavirus 2. "So, with other common DEG, the gene (B4GALNT2) can be a potential biomarker for revealing the connection between COVID-19 and associated comorbidities." (PMID 38957825, 2024). "Among them, B4GALNT2 was highly expressed in COVID-19 as well as diabetic peripheral neuropathic patients." (PMID 38957825, 2024). "Our comprehensive analysis revealed that four common genes, B4GALNT2, MTX1, POLR2J, and TUBB4B are differentially expressed in patients with both COVID-19 and diabetic peripheral neuropathy." (PMID 38957825, 2024).
female infertility (1 paper, 2013). Diminished or absent ability of a female to achieve conception. "Specific ovarian protein glycosylation by B4GALNT2 is proposed as a new mechanism of ovulation rate regulation in sheep, and could contribute to open new fields of investigation to understand female infertility pathogenesis." (PMID 24086150, 2013).
lung carcinoma (1 paper, 2022). "An increased expression of B4GALNT2 was also associated with tumourigenesis of lung cancer cells." (PMID 35044085, 2022).
malaria (1 paper, 2017). Malaria is a serious and sometimes fatal disease caused by a parasite that commonly infects a certain type of mosquito which feeds on humans. "Notably, the potential pathogen-driven selection acting on B4galnt2 in wild mice appears to be similar to the well-documented malaria-driven selection acting on the beta globin gene (HBB) in humans, where one allele confers resistance to a pathogen but carries a cost." (PMID 28806915, 2017).
non-small cell lung carcinoma (1 paper, 2021). A group of at least three distinct histological types of lung cancer, including non-small cell squamous cell carcinoma, adenocarcinoma, and large cell carcinoma. "On the other hand, for non-small cell lung cancer (NSCLC) cells, inhibition of B4GALNT2 suppressed proliferation and induced apoptosis in A549 cell lines." (PMID 34589428, 2021).
Von Willebrand disease (1 paper, 2013). von Willebrand disease (VWD) is a hereditary bleeding disorder caused by a genetic anomaly leading to quantitative, structural or functional abnormalities of the Willebrand factor (von Willebrand factor; VWF). "Indeed a switch of B4galnt2 gene expression from intestine epithelial cells to vascular endothelial cells, resulting in aberrant VWF glysosylation, explained the phenotypic characteristics of the RIIIS/J mice similar to human type 1 von Willebrand disease." (PMID 24086150, 2013).
cancer (15 papers, 2014 to 2023). A tumor composed of atypical neoplastic, often pleomorphic cells that invade other tissues. "Seven positions within the island (cg01147550-cg18208707 and cg02445664) displayed very low levels of methylation in both normal and the vast majority of tumor tissues, ruling out their major role in cancer-associated B4GALNT2 downregulation." (PMID 33919332, 2021). "Recently, two other dystroglycan-modifying glycosyltransferases, LARGE2 and B4GALNT2, were linked with the cancer-associated abnormal glycosylation of α-dystroglycan." (PMID 31054580, 2019). "Current data support the notion that high B4GALNT2 is causally related to a better prognosis because it can reduce stemness and capability to grow in poorly adherent conditions, and it increases the propensity to apoptosis and stimulates anti-cancer immunity." (PMID 32290493, 2020). "The reduced malignancy induced by the forced expression of B4GALNT2 in cancer cells by viral vectors also suggests its potential as a therapeutic agent." (PMID 34771437, 2021). "The mechanisms regulating B4GALNT2 expression in normal and cancer tissues are probably multifactorial and partially epigenetic." (PMID 34771437, 2021). "In this study, UALCAN was used to visualize the expression profile of B4GALNT2 across various TCGA cancers and paired‐normal samples." (PMID 34397142, 2021). "According to these data, B4GALNT2 mRNA level was nearly undetectable in the majority of cancer samples, but a remarkable number of cases retained a relatively high level of expression." (PMID 34771437, 2021). "On the transcriptome, B4GALNT2 induced the down-regulation of the stemness-associated gene SOX2 and modulated gene expression towards an attenuation of the cancer phenotype." (PMID 32290493, 2020). "In fact, in the cancer tissues of the majority of the patients, B4GALNT2 is virtually undetectable, while in a minority, a quite high activity is detectable." (PMID 32290493, 2020). "Transcriptomic data from The Cancer Genome Atlas (TCGA) database indicate that CRC patients with higher B4GALNT2 expression level in cancer tissues display longer overall survival." (PMID 32911675, 2020). "TCGA data confirm the general downregulation of B4GALNT2 in cancer tissues." (PMID 34771437, 2021). "Consistently, TCGA data analysis showed that in normal breast tissues as well as in the majority of BRCA tissues, the level of B4GALNT2 mRNA expression was nearly undetectable, although a minority of the cancer cases displayed a level of activity similar with that of colon." (PMID 34771437, 2021). "In conclusion, the regulation of B4GALNT2 in normal and cancer colon is complex and multifactorial." (PMID 34771437, 2021). "However, the methylation level in these positions is similar in the corresponding normal tissues, ruling out the possibility that a differential methylation of these sites can be responsible for the downregulation of B4GALNT2 in cancer." (PMID 34771437, 2021). "Consequently, these changes cannot be responsible for the general B4GALNT2 downregulation in cancer." (PMID 33919332, 2021). "Some genes, which appeared to be virtually switched off in B4GALNT2-expressing cells, are involved in the basic properties of cancer cells, such as stemness (SOX2, ROR1), epithelial to mesenchymal transition (EMT) (NID1, ALX1), and growth (FAM110B, PEG10, MID2)." (PMID 32290493, 2020). "Thus, we asked whether those genes that we found to be up-regulated in LS174T S2 and S11 cells were also up-regulated in patients showing high B4GALNT2 levels in cancer tissues and vice versa for genes displaying down-regulation in S2/S11 cells." (PMID 32290493, 2020). "Although the SDa blood group is not a significant transfusion risk, the expression of B4GALNT2 in porcine ECs, the induced antibody response seen in NHPs and the results of cancer vaccination studies suggest that B4GALNT2‐dependent pig glycans may be immunogenic in humans." (PMID 29604134, 2018).
cancer (continued). "While the use of sLe antigens as cancer markers has been debated since the 1980s and is already applied in the clinic (CA19.9), the use of Sda and/or B4GALNT2 as prognostic markers would be novel." (PMID 34771437, 2021). "B4GALNT2, SLC9A2 and COL1A1 were significantly altered in carcinoma compared to normal or adenomatous polyp tissue." (PMID 25423035, 2014). "To investigate the relationship between B4GALNT2 expression and stemness, we analyzed the three cell lines for the expression of aldehyde dehydrogenase (ALDH), reported to be a stem-cell and cancer-initiating cell marker in many tissues, including colon tissue." (PMID 32290493, 2020). "However, the promoter of B4GALNT2 and ST3GAL6 seems to be hypermethylated in cancer in contrast to the MGAT3 promoter, which is hypomethylated." (PMID 27429195, 2016).
infection (13 papers, 2015 to 2025). The state of being infected such as from the introduction of a foreign agent such as serum, vaccine, antigenic substance or organism. "B4galnt2 is expressed by intestinal epithelial cells and we previously demonstrated that B4galnt2-deficient mice are more resistant to infection with the intestinal facultative intracellular pathogen S. Typhimurium." (PMID 36033875, 2022). "B4GALNT2 is an enzyme that adds GalNAc to the sub-terminal galactose of α-2,3-linked sialic acid-containing glycans and can therefore confer resistance against infection of viruses with a preference for α-2,3-linked sialic acid." (PMID 37483287, 2023). "To test whether B4galnt2-glycans affect the susceptibility to extracellular pathogens, we infected B4galnt2 sufficient and deficient mice with C. rodentium and followed the infection kinetics." (PMID 36033875, 2022). "Moreover, heterozygous individuals are of particular interest in this study system, as they express B4galnt2 both in the blood vessels and the gastrointestinal tract, leaving them with a potential dual cost of prolonged bleeding and infection susceptibility." (PMID 28806915, 2017). "Thus, B4galnt2 expression in the gut epithelium influences the diversity and resistance of bacterial communities, which in turn is associated with the outcome of infection." (PMID 26133982, 2015). "Overexpression of B4GALNT2 resulted in interference with IAV WSN/33 infection through virus binding and internalization, although to a lesser degree than CMAS-deficient cells." (PMID 39887213, 2025). "B4GALNT2, not only suppressed infection by hPIV3, but also that of multiple other PMVs, including hPIV1, SeV and NDV." (PMID 40667754, 2025). "In order to test the hypothesis that variation in B4galnt2 expression mediates differences in susceptibility to pathogens in the wild, we examined intestinal (cecum) tissue for the presence of inflammation as an indicator of possible ongoing infection using histological analysis." (PMID 36683151, 2023). "We observed similar colonization of C. rodentium in B4galnt2−/− and B4galnt2+/− mice during early time points after infection." (PMID 36033875, 2022). "After infection with C. rodentium ΔfimA-H, fewer bacteria bound to both B4galnt2−/− and B4galnt2+/+epithelial monolayers." (PMID 36033875, 2022). "B4galnt2 gene expression was also down regulated upon infection which further corroborates the lectin staining results." (PMID 26133982, 2015). "Among the DEGs, B4GALNT2 is a glycosyltransferase responsible for synthesizing Sd(a)/Cad-antigen-like structures, which enhance intestinal barrier function, infection resistance, and immune homeostasis through glycosylation regulation, playing a crucial role in maintaining gut health." (PMID 40646804, 2025). "A previous report showed that B4GALNT2 overexpression preferentially impacts α2,3-sialic acid binding by adding N-acetylgalactosamine onto α2,3-sialic acid only and resulted in profound effects on infection with IAV strain PR/8 in A549 cells." (PMID 39887213, 2025). "Finally, we experimentally demonstrate that B4galnt2 plays a significant role in the severity of infection with a candidate pathogen belonging to a new subspecies of Morganella morganii, a clinically important pathogen in humans." (PMID 36683151, 2023). "However, on day 19 post infection (p.i.)B4galnt2+/− mice cleared the infection whereas clearance of bacteria in B4galnt2−/− mice was delayed until day 23 p.i.." (PMID 36033875, 2022). "Furthermore, the modification of α-2,3-linked sialic acid by B4GALNT2 could inhibit the binding of infectious bronchitis virus (IBV) to the host, as IBV also binds to α-2,3-linked sialic acid during infection." (PMID 37483287, 2023).
infection (continued). "Hence, targeted gene expression studies as well as glyco-profiling of the airway epithelium infected with SARS-CoV-2 virus can validate whether Sd(a) antigens predominate sLex antigens and the increased expression of B4GALNT2 is an adaptive mechanism to reduce the severity of the infection." (PMID 33435561, 2021). "Overexpression of B4GALNT2 alone did not affect infection for the four tested viruses in HEKΔSia cells." (PMID 40667754, 2025).
tumor (8 papers, 2018 to 2023). "A high B4GALNT2 expression was associated with 27 tumor restraining and 10 tumor promoting changes, suggesting its association with a low-malignancy molecular signature." (PMID 33919332, 2021). "Tumor-hypoxia-related studies that are directly relevant to B4GALNT2 and PKP1 in hypoxia are few and far between." (PMID 35757722, 2022). "Which reports the correlation between B4GALNT2 expression and methylation status of the 16 sites in tumor tissues, in some cases, methylation results in enhancement, rather than inhibition, of gene expression." (PMID 33919332, 2021). "In-vivo tumor formation experiments in mice revealed that knockdown of the B4GALNT2 gene in MDA-MB-231 cells inhibited their proliferation ability, in comparison with shCtrl transfectant tumors." (PMID 34589428, 2021). "In-vivo tumor formation experiments in mice revealed that knockdown of the B4GALNT2 gene in MDA-MB-231 cells inhibited their proliferation." (PMID 34589428, 2021). "In-vivo tumor formation experiments in mice were carried out upon success of in-vitro experiments, where it was found that knockdown of the B4GALNT2 gene in MDA-MB-231 cells inhibited their proliferation ability." (PMID 34589428, 2021).
heart diseases (1 paper, 2012). "Although the biological relationship between B4GALNT2 and human heart diseases has yet to be documented, AKAP7, DYRK1A and FAM19A2 have all been implicated in its etiology." (PMID 23176082, 2012).
inflammation (1 paper, 2015). Aberrant reaction of the microcirculation characterized by movement of fluid and leukocytes from the blood into extravascular tissues. "Fecal transfer experiments demonstrated a crucial role of the B4galnt2-dependent microbiota in conferring susceptibility to intestinal inflammation, while epithelial B4galnt2 expression facilitated epithelial invasion of S. Typhimurium." (PMID 26133982, 2015).
B4GALNT2 also shares sentences with these, for which no sentence is quoted: muscular dystrophy (3 papers); avian influenza (2); Congenital muscular dystrophy type 1A (1); embryonal carcinoma (1); hepatocellular carcinoma (1); influenza (1); metastatic melanoma (1); metastatic prostate carcinoma (1); myeloma (1); prostatic cancer (1); stomach cancer (1); Thrombocytopenia (1); triple-negative breast carcinoma (1).